SF1 (splicing factor 1)
Diseases named in the same sentence as SF1 in open-access papers (continued):
Sharing a sentence is not in itself a finding about the gene and the disease.
cryptorchidism (1 paper, 2023). The failure of one or both testes of a male fetus to descend from the abdomen into the scrotum during the late part of pregnancy. "The NR5A1/SF-1 c.437G>C/p.Gly146Ala variant is common in individuals with a DSD and has been suggested to act as a susceptibility factor for adrenal disease or cryptorchidism." (PMID 37432935, 2023).
cystic teratoma (1 paper, 2025). "SF1 and AR specifically highlighted the intraneural cell precursors of Leydig cells, which were previously identified in a published case of mature cystic teratoma of the ovary, and the adult ovarian Leydig cells." (PMID 40220034, 2025).
eosinophilia (1 paper, 2024). "As expected, both DGST-PIT1/SF1 and DGST-PIT1 showed strong eosinophilia, GH expression and alpha-subunit expression compared to SGST-PIT1 (p < 0.001 in all three analyses)." (PMID 38228887, 2024).
granulosa cell tumor (1 paper, 2015). A slow-growing, malignant tumor, characterize by the presence of granulosa-like cells and Call-Exner bodies, that is almost always found in the ovary. "In fact, a chromatin immunoprecipitation study indicated that SF-1 bound to the pII promoter in KGN cells, which are derived from human granulosa cell tumors." (PMID 26576867, 2015).
head and neck cancer (1 paper, 2023). A primary or metastatic malignant neoplasm affecting the head and neck. "In head and neck cancer, reduction of core splicing factor expression caused by hypoxia (i.e., SF1, SRSF1, SRSF3, and SRSF7) results in nearly 90% of IR-affected genes displaying high retention of introns in hypoxic compared with normal cells." (PMID 37506056, 2023).
hypogonadotropic hypogonadism (1 paper, 2016). Abnormal ovarian or testicular function due to insufficient hormonal stimulation from the hypothalamic-pituitary axis. "Mice with pituitary-specific disruption of SF-1 have markedly diminished levels of pituitary gonadotropins modeling hypogonadotropic hypogonadism." (PMID 27086651, 2016).
influenza (1 paper, 2011). An acute viral infection of the respiratory tract, occurring in isolated cases, in epidemics, or in pandemics; it is caused by serologically different strains of viruses (influenzaviruses) designated A, B, and C, has a 3-day incubation period, and usually lasts for 3 to 10 days. "Since Tat-SF1 knockdown in influenza-infected mammalian cells affected formation of vRNP particles, independent of RNA synthesis or processing, these studies raised the possibility that Cus2 could be playing a similar role as a chaperone for viral RNP assembly." (PMID 21283673, 2011). "Moreover, Tat-SF1 was shown to facilitate influenza replication via its role in viral packaging, as opposed to having a role in viral RNA synthesis." (PMID 21283673, 2011).
intestinal cancer (1 paper, 2020). "In conclusion, our studies provide important genetic evidence that SF1 levels can attenuate intestinal cancer initiation and development due to the strong driver ApcMin/+ mutation." (PMID 33202710, 2020).
intestinal polyp (1 paper, 2020). Discrete abnormal tissue masses that protrude into the lumen of the intestine. "Our studies found that the number of intestinal polyps in ApcMin/+;Sf1+/− mice was significantly lower compared to that in the ApcMin/+ sibling cohort, indicating that lowered SF1 can ameliorate intestinal polyp development." (PMID 33202710, 2020). "ApcMin/+;Sf1+/− and ApcMin/+ mice developed intestinal polyps by 4 months, and the majority of the polyps were of sizes between 1 mm to 5 mm." (PMID 33202710, 2020). "Using mouse models for our study, we found that mice expressing reduced SF1 levels develop fewer intestinal polyps." (PMID 33202710, 2020). "In contrast, it was reported that carcinogen treatment of Sf1+/− mice increased the number and size of intestinal polyps." (PMID 33202710, 2020). "The mixed 129/B6 genetic background may also be responsible for the wide range of polyp numbers (0 to 131) observed in our cohorts and as to why females of both ApcMin/+;Sf1+/− and ApcMin/+ cohorts developed higher numbers of intestinal polyps than males." (PMID 33202710, 2020). "Thus, therapeutic lowering of SF1 levels in the intestine could attenuate intestinal polyp development." (PMID 33202710, 2020).
liposarcoma (1 paper, 2012). A usually painless malignant tumor that arises from adipose tissue. "The beta-catenin/TCF4 pathway also modifies alternative splicing through modulation of expression of splicing factors SRp20 and SF1 and direct interaction with FUS/TLS (translocated in liposarcoma) and various other RNA-binding proteins, including p54nrb." (PMID 22682314, 2012).
liver disease (1 paper, 2024). "It has been observed that different liver disease models in mice display distinct profiles of trans-acting splicing factor 1 expression." (PMID 39834948, 2024).
metabolic syndrome (1 paper, 2018). A cluster of metabolic risk factors for CARDIOVASCULAR DISEASES and TYPE 2 DIABETES MELLITUS. "In summary, our data suggest that insulin contributes to the dysregulation of the HPA axis observed in metabolic syndrome by directly increasing the production of adrenal gland hormones through upregulation of SF-1 and the steroidogenic genes important for steroid hormone synthesis." (PMID 29567944, 2018).
metastatic cancer (1 paper, 2016). A carcinoma which has spread from the original site of growth to another anatomic site. "We were successful in diagnosing the patient as having ACC with metastatic liver cancer based on positive immunohistochemical staining of metastatic cancer for adrenocortical specific Ad4BP/SF1 and steroidogenic enzymes." (PMID 26772981, 2016).
metastatic tumor (1 paper, 2016). "Here we reported the first case of aldosterone-producing ACC diagnosed by immunohistochemical staining in only the metastatic tumor to detect both Ad4BP/SF1 and steroidogenic enzymes." (PMID 26772981, 2016). "Here we report the first case of aldosterone-producing ACC diagnosed by immunohistochemical staining in only the metastatic tumor to detect both Ad4BP/SF1 and steroidogenic enzymes." (PMID 26772981, 2016).
multiple myeloma (1 paper, 2025). "Others have reported that IL6 promoted the interaction of the TNIK/β-catenin/TCF4 complex (multiple myeloma cells:); transcriptional activity of the β-catenin/TCF4 complex is promoted by TNIK and inhibited by SF1, which induces an alternative splicing activity." (PMID 40003000, 2025).
oral squamous cell carcinoma (1 paper, 2021). "Similarly, the lncRNA UCA1 can bind and sponge miR-184, which directly decreases the expression of SF1, resulting in the upregulation of SF1-mediated AS to accelerate the proliferation and cisplatin resistance of oral squamous cell carcinoma." (PMID 33407694, 2021).
ovarian endometriosis (1 paper, 2025). A non-neoplastic disorder characterized by the growth of endometrial tissue in the ovaries. "Annisa and colleagues’ study demonstrates a statistically significant difference on methylation profiles of SF-1 in peritoneal endometriosis compared to control groups, as well as between peritoneal and ovarian endometriosis." (PMID 40792071, 2025).
polyp (1 paper, 2020). A usually exophytic mass attached to the underlying tissue by a broad base or a thin stalk. "Our aim was to determine the effect of reduced SF1 levels on polyp development due to the strong driver ApcMin/+ mutation." (PMID 33202710, 2020). "Our results show that congenitally reduced SF1 levels resulted in reduction of intestinal polyp development in ApcMin/+ mice." (PMID 33202710, 2020). "However, lower SF1 levels appears to be more important for lowering polyp incidence in females than in males because polyp numbers in ApcMin/+;Sf1+/− females were significantly decreased than in ApcMin/+ females." (PMID 33202710, 2020). "Thus, one possibility regarding the previously reported azoxymethane (AOM)-induced increase in polyp development in Sf1+/− mice could be due to greater propensity of AOM-induced driver mutations to persist in intestinal epithelial cells of SF1-deficient mice." (PMID 33202710, 2020). "Thus, SF1 levels in intestinal cells influence cellular transformation and polyp development." (PMID 33202710, 2020).
Primary amenorrhea (1 paper, 2010). "Among the 15 adolescents with primary amenorrhea and low testosterone concentration, we identified two new SRY mutations, five new SF1 mutations and one new LH receptor gene mutation." (PMID 20302644, 2010). "As this amounts to one third of our cohort, we suggest that the SF1 sequence should be systematically analyzed in girls with primary amenorrhea due to 46,XY DSD and low testosterone concentration, as well as in newborns with 46,XY DSD." (PMID 20302644, 2010). "In contrast, we identified five new SF1 mutations in this cohort (5/15), which amounts to one third of the cases of primary amenorrhea due to 46,XY DSD with low pl-T level and 5/31 of the cases of primary amenorrhea due to 46,XY DSD." (PMID 20302644, 2010). "We directly sequenced SRY, SF1 and WT1 genes in 15 adolescent girls with primary amenorrhea, low testosterone concentration, and XY karyotype, to determine the prevalence of mutations." (PMID 20302644, 2010). "We specifically focused on SRY, SF1 and WT1 because these genes have previously been reported to be implicated in adolescents presenting with primary amenorrhea due to 46,XY DSD in association with low pl-T, but no other signs." (PMID 20302644, 2010). "To conclude, the genetic analysis of low-testosterone primary amenorrhea due to 46,XY DSD is complex since several factors may be involved, including SRY, SF1, WT1 and LH receptor." (PMID 20302644, 2010).
renal cell carcinoma (1 paper, 2021). "In addition, ectopic adrenal tissue must be differentiated from urogenital tumors, in particular its mimickers, such as renal cell carcinoma and Sertoli Leydig cell tumor, that also partially share the immunophenotypic markers of the adrenal cortex (Melan-A, SF-1, inhibin)." (PMID 34095993, 2021).
Sertoli cell tumor (1 paper, 2025). A sex cord-stromal tumor of the testis or the ovary. "SF1 expression was mostly described in Sertoli cells and Sertoli cell tumors, where it is present in all reported cases." (PMID 39592485, 2025).
sterility (1 paper, 2021). "Global knockout of SF-1 abrogated gonad and adrenal development, resulting in early perinatal lethality, whereas ovarian granulosa cell-specific deletion of SF-1 resulted in sterility, fewer oocytes, and decreased follicle growth." (PMID 33693603, 2021).
teratoma (1 paper, 2025). A non-seminomatous germ cell tumor characterized by the presence of various tissues which correspond to the different germinal layers (endoderm, mesoderm, and ectoderm). "We have observed SF1-positive LC in both plexiform tissue of the teratoma and in the ovaries of a 70-year-old woman." (PMID 40220034, 2025).
testicular tumors (1 paper, 2020). "Our initial study combined Sf1+/− with mouse strains genetically predisposed to develop germ cell derived testicular tumors, where we found that congenital reduction of SF1 significantly decreased testicular tumors." (PMID 33202710, 2020).
Thrombocytosis (1 paper, 2024). Increased numbers of platelets in the peripheral blood. "Thrombocytosis (high platelet count > 450 000/μL) has previously been reported in individuals with DSD due to NR5A1/SF-1 variants, possibly indicating spleen dysfunction." (PMID 39479520, 2024).
tumor (86 papers, 2003 to 2026). "Analysis of both human and murine adrenal tissues has linked SF-1 overexpression to adrenocortical tumorigenesis, providing insights into the underlying mechanisms of tumor formation." (PMID 36835002, 2023). "Of note, the authors have encountered intraparenchymal pure spindle cell tumours that express sex cord‐stromal tumour markers such as SF1 but cannot be definitely classified as fibroma/thecoma or MGST." (PMID 41384702, 2026). "Adrenocortical tumor cells show dysregulated hormone secretion and transcription factor steroidogenic factor 1 (SF1) is significantly upregulated, distinguishing cortical from medullary tumors." (PMID 40190189, 2025). "The tumor origin was confirmed by one study through the evaluation of markers of adrenal cortical differentiation, as steroidogenic factor 1 (SF-1), melan-A and alpha-inhibin." (PMID 39890749, 2025). "Two patients with a gonadotroph tumor showed a positive expression of the SF1 factor and slight (i.e., at ± expression) in the case of Pit-1." (PMID 40002261, 2025). "Specifically, FOXL2 was included as a key marker for AGCT tumor cell detection, with SF1, calretinin, and inhibinα serving as additional controls to validate AGCT cell staining." (PMID 41042551, 2025). "The pathway of negative regulation for transforming growth factor beta (TGF-β) was enriched in SF1-lineage-associated CX3CR1+ macrophages and helped control the tumor growth." (PMID 38658971, 2024). "SOX2 was upregulated on RNA sequencing in those tumours with low or patchy SF-1 expression when compared with those with diffuse SF-1 expression." (PMID 38483762, 2024). "In a recent study, SF-1 immunoexpression in gonadotroph tumour follicular cells was proposed to reflect neuroplasticity, specifically transformation of neoplastic cells into follicular cells." (PMID 38483762, 2024). "Our results are consistent with previous findings that gonadotroph tumours expressed similar levels of SF-1 mRNA compared with other tumour types." (PMID 38483762, 2024). "Overall expression levels were rather low among FSH/LH-positive DGST-PIT1/SF1 with a median of 3% (range: 1–30%) immunopositive tumor cells." (PMID 38228887, 2024). "Immunohistochemically, the tumor was positive for vimentin, SF1, CD56, and beta-catenin, which aligns with findings reported in the literature." (PMID 40071053, 2024). "Corticotroph tumours were characterized by tumours stained positively for T-box family member TBX19 (TPIT), while gonadotroph tumours were characterized by positivity for steroidogenic factor (SF-1)." (PMID 38756997, 2024). "In general, PitNETs are classified based on tumor cell lineages identified by immunohistochemical analysis of the main three TFs (SF1, PIT1 and TPIT) and the blood serum levels of pituitary hormones secreted by pituitary tumor hormone-secreting cells." (PMID 39114291, 2024). "In doubtful cases, immunohistochemistry for SF1 is the most sensitive and specific marker available to establish if the tumor is of adrenocortical origin, with a sensitivity of 98% and a specificity of 100%." (PMID 39129823, 2024). "TGFBR3L staining was present in 52% (n = 60) of the gonadotroph tumours, and in one double-PitNET (positive for FSHβ and SF-1 in some cells, and for ACTH and T-Pit in others), while all other tumours were negative." (PMID 36952069, 2023). "After 7 days of 3D NCI-H295R tumor construct culture, we observed expression of SF-1, Melan-A and, inhibin α are expressed as in 2D culture." (PMID 37726363, 2023). "Tumor cells express SF1 in 100% of the cases, inhibin in 82–98%, WT1 in 96%, CD99 in 68–86%, AE1/AE3 in 65%, and calretinin in 50–60%." (PMID 38136408, 2023). "ACC tumor constructs showed expression of biomarkers associated with ACC, including SF-1, Melan A, and inhibin α." (PMID 37726363, 2023).
tumor (continued). "Together, these results suggested that cells in node I were capable of hijacking the expression of multiple splicing factors, such as SRSF1 and SF1, apparently leading to dysfunctional gene splicing related to prosurvival pathways and tumor progression." (PMID 37308475, 2023). "A recent case series describing plurihormonal PitNETs expressing both PIT1 and SF1 has demonstrated that these tumours can be variable in their histological characteristics and clinical presentation." (PMID 37851558, 2023). "Multilineage pituitary transcription factor 1 (PIT1) and steroidogenic factor 1 (SF1) PitNETs are a rare and relatively newly described tumour subtype." (PMID 37851558, 2023). "Similar to the adult type, tumor cells express sex cord–stromal markers (SF1, inhibin, calretinin, WT1, FOXL2)." (PMID 38136408, 2023). "As a result, each of the samples showed clear nuclear immuno-reactivity with antibodies against SF-1 over the entire tumor tissue sample area." (PMID 36497102, 2022). "Immunohistochemical study in Chen’s case showed that tumor cells are diffusely positive for SF1, calretinin and SMA, and focally positive for cytokeratin AE1/3 and ER." (PMID 36428715, 2022). "In double PitNETs two areas of tumor tissue with distinct expression of PIT-1 or SF-1 can be observed." (PMID 36497102, 2022). "Recent advancements in targeted reprogramming [like selective ablation of Wt1 in Ctnnb1 (cadherin-associated protein β1) over-expressing Sc results into Lc cell-like tumor development, manipulation of SF1, GATA4,etc." (PMID 36686449, 2022). "Within the PIT1 lineage tumours, co-expression with SF1 was observed in all six cases, with one also expressing TPIT." (PMID 36271964, 2022). "Immunohistochemistry showed that the tumor cells were diffusely positive for SF-1 and Ki-67, partially positive for inhibin, and negative for CAM5.2, CK7, CK20, C-KIT, CD30, LCA, GATA-3, TTF-1, and PAX8." (PMID 36335378, 2022). "Co‐staining of rat tumor tissues for known markers of NF‐PitNETs (i.e., αGSU and the transcription factor SF‐1) and for Tie2 showed that the receptor is co‐expressed with both proteins in the tumor cells." (PMID 35266635, 2022). "There were 101 (89.3%) tumours arising from a distinct cell lineage (either PIT1, SF1 or TPIT) with tumours of SF1 lineage forming the larger group (39.8%) followed closely by PIT1 lineage (37.1%) and TPIT (12.4%)." (PMID 36271964, 2022). "Immunohistochemistry analyses identified that PIT1 cell lineage marker dominates in four PitNETs, gonadotroph PitNET marker NR5A1 (SF1) is the most abundant in five tumours and corticotroph cell lineage marker TBX19 (TPIT) has highest expression in one PitNET." (PMID 36026497, 2022). "As Sf-1:Hoxb9 adrenals showed an increase in Sf-1 expression, we investigated the levels of this gene in the tumours." (PMID 33214683, 2021). "In two cases of tumors expressing more than one TF, the gene expression profile corresponds to the IHC profile in the triple PitNET, whereas the results are disparate in the double PIT1 + SF1 tumor." (PMID 34758873, 2021). "The potential role of TGFBR3L in tumorigenesis related to SF-1 needs to be explored in other neoplasms." (PMID 33396509, 2020). "LRH-1 and SF-1 modulators are highly sought as treatments for metabolic and neoplastic diseases, and RJW100 has one of the few scaffolds shown to activate them." (PMID 33335203, 2020). ", we detected a highly significant SF-1 overexpression in the pediatric ACC tumor model SJ-ACC3 (348.2± 27.4%, p < 0.001 vs. MUC-1) and almost no detectable SF-1 expression in SW-13 xenografts (0.03± 0.0%, p < 0.001vs." (PMID 27764813, 2016). "SW-13-xenografts furthermore demonstrated an abrogation of both important markers, SF-1 and EGF-R, underlining the questionable value of SW-13 as tumor model for ACC." (PMID 27764813, 2016). "SF-1 expression was abundant in the stromal cells but was also present to a lesser degree in the epithelial tumor cells." (PMID 23190574, 2012).